DISC1 (DISC1 scaffold protein)
Description:
Involved in the regulation of multiple aspects of embryonic and adult neurogenesis. Required for neural progenitor proliferation in the ventrical/subventrical zone during embryonic brain development and in the adult dentate gyrus of the hippocampus (By similarity). Participates in the Wnt-mediated neural progenitor proliferation as a positive regulator by modulating GSK3B activity and CTNNB1 abundance. Plays a role as a modulator of the AKT-mTOR signaling pathway controlling the tempo of the process of newborn neurons integration during adult neurogenesis, including neuron positioning, dendritic development and synapse formation (By similarity). Inhibits the activation of AKT-mTOR signaling upon interaction with CCDC88A (By similarity). Regulates the migration of early-born granule cell precursors toward the dentate gyrus during the hippocampal development. Inhibits ATF4 transcription factor activity in neurons by disrupting ATF4 dimerization and DNA-binding (By similarity). Plays a role, together with PCNT, in the microtubule network formation.
Synonyms: C1orf136; SCZD9
Tractability: Small molecule: a structure with a bound ligand is known. PROTAC: UniProt records ubiquitination sites on it; ubiquitination databases record sites on it.
Gene: Protein-coding gene on chromosome 1 (231,626,790 to 232,041,272, forward strand). Ensembl gene ENSG00000162946.
Subcellular location: Cytoplasm; Cytoplasm, cytoskeleton; Mitochondrion; Cytoplasm, cytoskeleton, microtubule organizing center, centrosome; Postsynaptic density
Subcellular location (Human Protein Atlas): Cytosol; Intermediate filaments
Gene Ontology:
Molecular function: identical protein binding; protein binding; molecular adaptor activity; kinesin binding; protein-containing complex binding
Biological process: microtubule cytoskeleton organization; neuron migration; non-motile cilium assembly; positive regulation of neuroblast proliferation; positive regulation of Wnt signaling pathway; brain development; cilium assembly; canonical Wnt signaling pathway; cell proliferation in forebrain; cerebral cortex radially oriented cell migration; nervous system development; positive regulation of axon extension; positive regulation of cell-matrix adhesion; positive regulation of neuron projection development; protein localization to centrosome; pyramidal neuron migration to cerebral cortex; regulation of dendritic spine development; regulation of neuron projection development; regulation of postsynapse organization; regulation of synapse maturation; response to electrical stimulus; TOR signaling
Cellular component: centrosome; ciliary base; cytoplasm; cytosol; GABA-ergic synapse; glutamatergic synapse; intermediate filament cytoskeleton; mitochondrion; postsynaptic density; presynapse; axon; cell body; central region of growth cone; ciliary basal body; cytoskeleton; dynein complex; kinesin complex; microtubule; perinuclear region of cytoplasm; synaptic vesicle
Genetic constraint (gnomAD): Loss-of-function variants: 60 observed, 83.29 expected, observed/expected ratio (o/e) 0.72, 90% interval 0.58 to 0.89. The upper end of that interval is the gene's LOEUF score, 0.89, which puts it in group 3 of 6, group 1 being the genes least tolerant of losing a copy. Missense variants: 983 observed, 1,063.3 expected, observed/expected ratio (o/e) 0.92, 90% interval 0.88 to 0.97. Synonymous variants: 407 observed, 422.92 expected, observed/expected ratio (o/e) 0.96, 90% interval 0.89 to 1.04.
Homologues: Orthologues: chimpanzee DISC1 (93% identical), macaque DISC1 (90% identical), pig DISC1 (68% identical), rabbit DISC1 (68% identical), dog DISC1 (67% identical), mouse Disc1 (56% identical), rat Disc1 (54% identical), guinea pig DISC1 (54% identical), zebrafish disc1 (26% identical).
Diseases named in the same sentence as DISC1 in open-access papers:
DISC1 is named in the same sentence as 87 diseases in open-access papers, as found by Europe PMC text mining. Sharing a sentence is not in itself a finding about the gene and the disease. The quoted sentences say what the papers report.
schizophrenia (428 papers, 2005 to 2026). A major psychotic disorder characterized by abnormalities in the perception or expression of reality. "The schizophrenia defect 1 gene (disrupted-in-schizophrenia 1, DISC1) primarily encodes the synaptic protein DISC1, which is expressed early in development." (PMID 40537021, 2026). "Genetic analysis showed that the DISC1 gene is considered to be a highly associated genetic factor in schizophrenia in humans." (PMID 40537021, 2026). "Mutations at the DISC1 locus are strongly associated with a spectrum of mental illnesses such as schizophrenia and depression." (PMID 41997921, 2026). "DISC1 is expressed in several subcellular compartments, including mitochondria, and is a risk factor for several neurological disorders such as schizophrenia and bipolar disorder." (PMID 40537021, 2026). "Genetic variations in DISC1 were found to modulate prefrontal-limbic connectivity in schizophrenia, and hereditary spastic paraplegia was strongly associated with mutations in SPG4 and SPG11, leading to progressive degeneration of corticospinal tracts." (PMID 40360788, 2025). "To address these questions and comprehend the impact of point mutations in DISC1 on the pathophysiology of schizophrenia and related CMIs, we employed a combination of biophysical techniques and structural biology applications." (PMID 40503182, 2025). "Among these, DISC1 has long been recognized as a genetic risk factor for schizophrenia and affective disorders, and GWAS have linked the loci associated with the DISC1 interactome to suicidality." (PMID 41465140, 2025). "DISC1 is one of the genes known to be strongly associated with the development of many mental disorders, particularly schizophrenia, and is thus an established genetic risk factor." (PMID 41465140, 2025). "For example, DISC1 has long been recognized as a genetic risk factor for schizophrenia and affective disorders, and GWAS have linked the loci associated with the DISC1 interactome to suicidality." (PMID 41465140, 2025). "A molecule that plays multiple roles in the nervous system called DISC1 (disrupted in schizophrenia 1) is associated with schizophrenia." (PMID 39940735, 2025). "Alterations in genes related to this pathway, such as Disrupted in Schizophrenia 1 (DISC1), have been linked to schizophrenia." (PMID 40650013, 2025). "In 2007, Camargo and colleagues identified MACF1 as a protein interacting with two schizophrenia risk genes, DISC1 (disrupted in schizophrenia 1) and DTNBP1 (dysbindin)." (PMID 39781307, 2024). "DISC1 variants were found in other psychiatric disorders, which was emphasized by its name derived from “disrupted in schizophrenia”." (PMID 38891944, 2024). "The misexpression of Disc1 is associated with an increased risk of mental illness, and polymorphisms of Disc1 are known genetic risk factors for several psychiatric disorders including schizophrenia." (PMID 39199302, 2024). "The genetic evidence regarding the association between DISC1 and schizophrenia shows inconsistencies." (PMID 38920990, 2024). "Three common disrupted in schizophrenia 1 (DISC1) gene variants as well as several rare and ultrarare variants, have been associated with schizophrenia." (PMID 37107350, 2023). "DISC1 is a susceptibility gene for schizophrenia and putatively for other psychiatric disorders, initially discovered in a Scottish family with a high frequency of mental disorders." (PMID 36831241, 2023). "Several reports have shown that common variants of DISC1 are associated with endophenotypes relevant to schizophrenia, including reduced gray matter volume and poor working memory." (PMID 36831241, 2023). "Here we evaluated the validity of a novel gene–gene interaction mouse model of SCZ using mice with mutations in genes associated with schizophrenia, DISC1 and RELN." (PMID 38283751, 2023).
schizophrenia (continued). "The analysis resulted that the gene set extracted by the systematic review is strongly associated with genes differentially expressed in schizophrenia (p ≤ 0.0001422) with reference to DISC1 and NRG1." (PMID 36831241, 2023). "Several mouse models carrying different DISC1 mutations have been generated to explore the function of DISC1 on schizophrenia pathology." (PMID 36590092, 2022). "This is consistent with studies showing that interaction of mutated Disrupted-In-Schizophrenia-1 (DISC1) protein with SR decreases D-serine levels and produces schizophrenia-like symptoms in mice." (PMID 35410329, 2022). "KALRN, TRIO, and DISC1 misexpression or mutation are implicated in attention deficit hyperactivity disorder, autism, bipolar disorder, schizophrenia, and other conditions." (PMID 35440587, 2022). "Several DISC1 splicing variants are upregulated in the hippocampi of schizophrenia patients, where significant pathological changes occur at the clinical high risk (CHR) stage of the onset of schizophrenia." (PMID 36131044, 2022). "To conclude, deletion of DISC1 exon 3 in oligodendroglia is sufficient to induce schizophrenia-like behavioral abnormalities and cause significant synaptic alterations." (PMID 36131044, 2022). "The study of the DISC-1 point mutation in a mouse model of schizophrenia revealed that one of the possible mechanisms of aggregates formation represented an increase in the intermolecular cohesion of the protein." (PMID 36430976, 2022). "Mutations in Disc1 lead to alterations in neuronal architecture and cognition, that have been reported for schizophrenia, bipolar disorder, and major depression." (PMID 34844990, 2022). "VENs show high expression of the DISC1 schizophrenia-associated gene, and the number of VENs is correlated with schizophrenia age of onset." (PMID 35771867, 2022). "Our findings reveal the pathogenetic role of OPC-specific DISC1-Δ3 variant in the onset of schizophrenia and highlight the therapeutic potential of Wif1 as an alternative target for the treatment of this disease." (PMID 36131044, 2022). "Of note, changes in cell-cell adhesion have been associated with other genetic risk factors for schizophrenia, such as in DISC1 and NRXN1 mutations." (PMID 36581615, 2022). "DISC1 encodes disrupted in schizophrenia 1, which is involved in neurogenesis and astrogenesis, and is a positive regulator of WNT signaling and negative regulator of PI3K/AKT/mTOR signaling." (PMID 35440587, 2022). "Using a rat model to over-express the schizophrenia risk gene DISC1, researchers discovered a number of dysregulated genes in the rats’ peripheral blood mononuclear cells." (PMID 35844244, 2022). "The schizophrenia risk gene Disrupted-in-Schizophrenia 1 (DISC1), localizes to the outer surface of the ER and has been found to regulate ER Ca2+ dynamics." (PMID 35844244, 2022). "To distinguish the contribution of hypertrophic OPCs from the myelin deficiency during the onset of schizophrenia, we investigated conditional DISC1 exon 3 deletion at different ages." (PMID 36131044, 2022). "Mechanistically, we demonstrated that mice with enhanced DISC1-Δ3 variant expression in OPCs display schizophrenia-like behaviors and synaptic defects, both driven by the overactivated Wnt/β-catenin-Wnt inhibitory factor 1 (Wif1) cascade." (PMID 36131044, 2022). "DISC1 emerged as a schizophrenia susceptible gene since its genomic disruption, while frameshift mutation, or single nucleotide polymorphisms (SNPs) were associated with familial schizophrenia." (PMID 36131044, 2022). "The protein binding interaction between Nde1, Ndel1, and DISC1 is well-established and the genetic interaction between Nde1/Ndel1 and DISC1 is associated with an increased risk for schizophrenia." (PMID 35493069, 2022). "In patients with schizophrenia, abnormal expression of DISC1 can decrease PAK activity and cause defects in axonal guidance and neuronal connectivity." (PMID 33306168, 2022).
schizophrenia (continued). "In DISC1 loss of function mice displaying schizophrenia-like behavior, disruption of GSK-3-DISC1 interactions, or treatment with SB-216763, reduced hyper-locomotion and produced anti-depressive like activity in FST." (PMID 35126052, 2021). "A translocation in DISC1 was reported in a Scottish pedigree as a rare but penetrant risk factor for several mental illnesses including schizophrenia, depression, and bipolar disorder." (PMID 33949949, 2021). "DISC1 is now established as a risk factor for schizophrenia and other major psychiatric illness and is involved in aspects of adult progenitor proliferation, neurogenesis, neurite outgrowth, cytoskeletal modulation, signal transduction, and CTNNB1 abundance." (PMID 34831151, 2021). "The human SCN1A gene (the ortholog of the zebrafish scn1lab gene) is associated with Dravet’s syndrome (where patients have epilepsy and developmental disorders including autism), and DISC1 is associated with schizophrenia." (PMID 34613782, 2021). "DISC1 regulates cAMP levels; hence, its loss of function, as observed in schizophrenia, causes increased cAMP levels, which in turn increase HCN channel activity and lead to spine loss." (PMID 34149352, 2021). "We previously identified a causal link between a rare patient mutation in DISC1 (disrupted-in-schizophrenia 1) and synaptic deficits in cortical neurons differentiated from isogenic patient-derived induced pluripotent stem cells (iPSCs)." (PMID 33658519, 2021). "Previously, it was reported that dysbindin forms a functional complex with disrupted-in-schizophrenia 1 (DISC1), another schizophrenia susceptibility factor." (PMID 33461576, 2021). "Disruption of the Disc1 gene has been associated with susceptibility for various neuropsychiatric disorders, including schizophrenia." (PMID 34072341, 2021). "FEZ1 is known to directly bind to DISC1 (disrupted in schizophrenia 1) protein, an important SZ risk, to regulate neurite outgrowth." (PMID 33446247, 2021). "We and others have previously identified that DISC1 acts as a positive regulator of mitochondrial trafficking, with varying inhibitory effects of schizophrenia-associated mutations reported." (PMID 32637409, 2020). "DISC1 is a gene disrupted by a chromosomal translocation that has been linked to psychiatric conditions, including schizophrenia, but its association with the disorder remains controversial." (PMID 32425837, 2020). "The disrupted in schizophrenia 1 (DISC1) protein is implicated in major mental illnesses including schizophrenia and bipolar disorder." (PMID 32637409, 2020). "The DISC1 R264Q variant has previously been associated with schizophrenia, and has been reported to impair GSK-3 signaling and neurodevelopment." (PMID 32493513, 2020). "DISC1 was originally implicated in schizophrenia in a single family with a drastic mutation, a chromosomal translocation severing the mid-point of the gene (aa 598)." (PMID 32493513, 2020). "The increased DISC1-D2R complex levels with DISC1 R264Q provides further evidence for the mechanism by which schizophrenia-associated DISC1 variants can increase disease susceptibility." (PMID 32493513, 2020). "Some common DISC1 variants have also been associated with schizophrenia in the general population, but those located far from the chromosomal translocation breakpoint likely have a different functional impact." (PMID 32493513, 2020). "A disease-associated mutation in the DISC1 gene that has generated considerable interest is that of a 4-base-pair deletion, first described in an American kindred with schizophrenia and schizoaffective disorder." (PMID 32637409, 2020). "Here, we demonstrate that the mutDISC1 encoded by the schizophrenia-associated 4-bp deletion in DISC1 impairs anterograde mitochondrial transport in neuronal axons." (PMID 32637409, 2020).
schizophrenia (continued). "The DISC1-D2R protein complex and enhancement by the R264Q variant provides additional insights into schizophrenia biology because we found previously that schizophrenia patients in general have higher DISC1-D2R complex levels." (PMID 32493513, 2020). "Disrupted In Schizophrenia 1 (DISC1), which is deficient in patients with schizophrenia, depression, and bipolar disorder, is expressed in adult mouse NSCs and regulates their proliferation." (PMID 32324743, 2020). "Because some common DISC1 variants have been associated with schizophrenia, we investigated possible functional effects on DISC1-D2R complex formation and GSK3 α/β Ser21/9 phosphorylation." (PMID 32493513, 2020). "The DISC1 “disrupted in the schizophrenia 1 gene” when mutated increases the risk of schizophrenia in humans, and DISC1 mutations impair LTP and LTD in mice." (PMID 32132582, 2020). "When the DISC1 protein are disrupted it predisposes the carrier to a number of mental health disorders including schizophrenia." (PMID 32995075, 2020). "Among a number of susceptibility genes involved in schizophrenia, the DISC1 (disrupted in schizophrenia 1) gene is one of the best characterized." (PMID 32796766, 2020). "We found that this schizophrenia-associated deletion in DISC1 drastically reduces mitochondrial transport in hippocampal axons and dendrites." (PMID 32637409, 2020). "The DISC1 (disrupted in sсhizophrenia 1) gene is associated with brain dysfunctions, which are involvedin a variety of mental disorders, such as schizophrenia, depression and bipolar disorder." (PMID 33959693, 2020). "Accumulating evidence implicates the disrupted-in-schizophrenia 1 protein (DISC1) as a strong candidate susceptibility factor for schizophrenia." (PMID 31057438, 2019). "One of the most intensively studied genes associated with schizophrenia is DISC1, and was first identified with a high incidence of depression, schizophrenia, and bipolar disorder in a Scottish pedigree." (PMID 31151179, 2019). "DISC1, the perturbation of which has been implicated in the pathophysiology of a number of mental disorders, including schizophrenia, major depressive disorder and bipolar disorder, binds to SR and stabilizes it." (PMID 30787885, 2019). "Disrupted-in-schizophrenia 1 (DISC1), one of the schizophrenia susceptibility gene, has been shown to regulate NSC proliferation by regulating Akt-glycogen synthase kinase (GSK) 3β signaling." (PMID 31819047, 2019). "Consistently, studies have showed that schizophrenia risk genes (including DISC1, RELN and GLT8D1) have important role in brain development through regulating proliferation and differentiation of neural stem cells." (PMID 30737407, 2019). "We found increased lactate in the dorsolateral prefrontal cortex (p = 0.043, n = 16/group) in schizophrenia, as well as in frontal cortical neurons differentiated from a subject with schizophrenia with the DISC1 mutation (p = 0.032)." (PMID 30911039, 2019). "Both human studies and animal models implicate disrupted-in-schizophrenia 1 (DISC1) gene as a strong susceptibility factor for schizophrenia." (PMID 31057438, 2019). "Early studies aimed at identifying underlying genetic components in schizophrenia highlighted both rare disruptions and common variants in a number of candidate genes such as Disrupted In Schizophrenia 1 (DISC1)." (PMID 30761022, 2019). "Various animal models based on DISC1 dysfunction have been generated since its identification as a robust risk factor in schizophrenia." (PMID 31057438, 2019). "Abnormal DISC1 has been proposed to augment the risk of schizophrenia, bipolar disorders, and recurrent major depression, especially when combined with environmental stressors acting at different developmental time points." (PMID 30617212, 2019). "According to recent studies, DISC1 is considered to be the primary susceptibility gene for schizophrenia." (PMID 30409224, 2018).